BRF2 (BRF2 general transcription factor IIIB subunit)
Diseases named in the same sentence as BRF2 in open-access papers (continued):
Sharing a sentence is not in itself a finding about the gene and the disease.
cancer (continued). "The TFIIIB subunit BRF2 is differentially expressed in cancer cells and overexpressed in a subset of cancer patients." (PMID 33176745, 2020). "We queried Oncomine, containing 715 data sets (86,733 samples), to determine the frequency of BRF2 alterations in human cancers." (PMID 33176745, 2020). "Tumors with the highest BRF2 expression showed 86 genes differentially expressed, with functions in posttranscriptional modification, gene expression, and cancer." (PMID 32611613, 2020). "Deregulation of the RNA polymerase III specific TFIIIB subunit BRF2 occurs in subtypes of human cancers." (PMID 33176745, 2020). "Together, these data suggest a comprehensive analysis of human cancer data sets to identify BRF2 alterations and clinical outcomes is warranted." (PMID 33176745, 2020). "The disease summary analysis for BRF2 identified 7 significant unique analyses of BRF2 expression out of 372 unique analyses in studies comparing cancer versus normal tissue." (PMID 33176745, 2020). "We have proved that miR-425-5p downregulated BRF2 expression and also miR-425-5p inhibitslung cancer cell growth." (PMID 31964245, 2020). "Conversely, to test the functional consequences of decreasing Brf2 activity during oxidative stress in cancer cells, we reduced the levels of Brf2 via small interfering RNA (siRNA) in A549 cells challenged with t-BHP." (PMID 26638071, 2015). "It is noteworthy that another polyphenol, EGCG that is enriched in green tea, also affects expression of BRF1 and BRF2 selectively, but in this case elicits an inhibitory effect, in keeping with its anti-cancer activity." (PMID 26573593, 2015). "Several studies have shown that BRF2 is overexpressed in several types of cancer and suggest the oncogenic role of BRF2." (PMID 24523874, 2014). "Diffuse nuclear staining of BRF2 protein at various intensities was observed in cancer cells, but BRF2 was barely detected in normal lung tissues." (PMID 24523874, 2014). "BRF2 has been shown to be highly overexpressed in a variety of cancers including gastric, kidney and melanoma cancers." (PMID 24523874, 2014). "Based on this analysis, we determined that in studies comparing cancer versus normal tissue, BRF2 is highly overexpressed in datasets focused on gastric, kidney and melanoma cancers." (PMID 21518452, 2011). "We have demonstrated that the TFIIIB subunits Brf1 and Brf2 are differentially expressed at the mRNA level in a variety of cancer cells." (PMID 18700021, 2008). "We also demonstrate, that Brf1-dependent VAI transcription was significantly higher than the Brf2-dependent U6 snRNA transcription in all cancer cell lines tested." (PMID 18700021, 2008). "Here, we report that the TFIIIB subunits Brf1 and Brf2 are differentially expressed in a variety of cancer cell lines." (PMID 18700021, 2008). "We demonstrate that Brf1 and Brf2 mRNA are differentially expressed in a variety of cancer cells and that the Brf2 promoter is more active than the Brf1 promoter in all cell lines tested." (PMID 18700021, 2008). "BRF2 is overexpressed in many malignant tumors and plays a crucial role in carcinogenesis." (PMID 40610422, 2025). "Thus, BRF2 plays an important role in the regulation of protein synthesis, with implications for proliferating cancer cells." (PMID 36902501, 2023). "The TFIIIB subunits, BRF1,20, 21, 22, 23 required for gene‐internal promoters, and BRF2,12, 16, 24, 25, 26, 27, 28, 29, 30, 31, 32, 33 required for gene‐external promoters, distinguish the two forms and have been well‐studied in various human cancers." (PMID 36305848, 2023). "For example, BRF2 has been classified as a novel proto-oncogene in human cancers." (PMID 35406430, 2022). "In this study, BRF2 importantly promotes cancer cell proliferation, migration, and invasion." (PMID 35884580, 2022). "The TFIIIB subunits TBP, BRF1, and BRF2 have begun to be studied in specific human cancers." (PMID 35406430, 2022).
cancer (continued). "Moreover, high baseline levels of BRF2 have been observed in cancer cell lines that are subjected to prolonged oxidative stress." (PMID 34359683, 2021). "However, BRF2 plays a key role in protecting cancer cells against oxidative stress and our data additionally suggest that BRF2 plays a role in DDR regulation." (PMID 34359683, 2021). "BRF2 is regulated by chemopreventive agents in cancer cells and a mouse model." (PMID 33176745, 2020). "Using a threshold p-value of 1E-4, a 2 a fold-change for BRF2 gene expression compared to the controls, and a gene rank percentile of 10%, we demonstrate that BRF2 is both over- and under-expressed across the analyzed human cancers." (PMID 33176745, 2020). "In the cancer versus cancer data sets, BRF2 is both over- and under-expressed." (PMID 33176745, 2020). "In our study, we firstlyshowed the interaction of miR-425-5p and BRF2 in the NSCLC cancer type." (PMID 31964245, 2020). "Direct redox-sensing by the RNA polymerase III core transcription factor Brf2 couples cellular responses to oxidative stress and regulation of transcriptional output, contributing to the ability of cancer cells to evade death induced by reactive oxygen species." (PMID 26638071, 2015). "However, we only found a trend towards the correlation between upregulated expression level of BRF2 and downregulated expression level of snail in cancer tissues by Mann-Whitney U test (P > 0.05)." (PMID 24738062, 2014). "BRF2 has been shown to be highly overexpressed in a variety of cancers including gastric, kidney, and melanoma cancers, and our previous studies have pointed out that BRF2 protein overexpression is common in early-stage ESCC and significantly correlated with tumor prognosis and relapse." (PMID 24738062, 2014). "Interestingly, analysis of the BRF2 disease summary shows that BRF2 is highly expressed on the basis of outlier gene expression using a method called COPA (cancer outlier profile analysis)." (PMID 21518452, 2011). "Hence, we queried the Oncomine database to systematically assess gene expression levels of BRF2 in a variety of carcinomas." (PMID 21518452, 2011). "Thus, using the Oncomine database, we performed a disease summary for BRF2 to determine if BRF2 overexpression was significant in various carcinomas." (PMID 21518452, 2011). "Taken together, we reason that deregulation of Brf1 and Brf2 expression could be a key mechanism responsible for the observed deregulation of RNA pol III transcription in cancer cells." (PMID 18700021, 2008). "Therefore, it has been speculated that the high levels of BRF2 expression in cancer cell lines assist in maintaining the sufficient expression of selenoproteins in order to detoxify ROS and preserve redox homeostasis." (PMID 34359683, 2021). "Similarly, BRF2 is both over- and under- expressed in the multi-cancer data sets." (PMID 33176745, 2020). "Furthermore, the multivariate analyses identified BRF2 protein overexpression (P = 0.025), clinical stage (P = 0.017), E-cadherin protein overexpression (P = 0.020), and the differentiation of cancer (P = 0.046) as independent prognostic factors for progression-free survival." (PMID 24738062, 2014). "TFIIIB, an RNA polymerase III specific transcription factor has been found to be deregulated in human cancers with much of the research focused on the TBP, BRF1, and BRF2 subunits." (PMID 36305848, 2023). "It was conspicuous that in the investigated cancer cell lines and near-normal breast cell line (MCF10A), the expression of BRF2 was upregulated after ionizing radiation." (PMID 34359683, 2021). "It is established that RNA pol III is often deregulated in cancers and specific elevation of RNA pol III transcripts and RNA pol III transcription factors such as U6 snRNA and BRF2 is a feature of both transformed cells and cancers." (PMID 21518452, 2011). "IHC staining was performed to determine the expression of BRF2 protein in cancer tissues and adjacent non-cancerous tissues of 30 LUSC patients." (PMID 40610422, 2025).
cancer (continued). "In this study, we found that expression of BRF2 was higher in liver tumor tissues and cancer cells compared with normal adjacent tissues and noncancerous cells." (PMID 36927769, 2023). "In order to study the characteristics of BRF2 in live cancer cells, siRNA targeting BRF2 or a negative control (si-NC) was transfected into Huh-7 and SMMC-7721 cells." (PMID 36927769, 2023). "Furthermore, we carried out in silico screening to target the BRF2-TBP-DNA complex and identified potential cancer drugs as candidates." (PMID 34359683, 2021). "BRF2, a subunit of the RNA polymerase III transcription complex, is upregulated in a wide variety of cancers and is a potential therapeutic target; however, no effective drugs are available to target BRF2." (PMID 34359683, 2021). "We further demonstrate that the Brf1 and Brf2 promoters differ in activity in cancer cell lines, and VAI transcription is universally elevated, as compared to U6 snRNA transcription, in breast, prostate and cancer cell lines." (PMID 18700021, 2008). "We speculate that out of the 478 unique analyses, the 45 analyses which have a significant decrease of BRF2 expression demonstrates that BRF2 overexpression may not be universal to all cancer patients." (PMID 21518452, 2011). "To investigate the status of BRF2 gene expression in NSCLC, we used Real-time PCR to measure the mRNA expression in 12 pairs of primary cancer tumors and adjacent noncancerous specimens." (PMID 24523874, 2014). "To investigate the status of BRF2 gene expression in NSCLC, we used real-time PCR to measure the mRNA expression in 14 pairs of primary cancer tumors and adjacent noncancerous specimens." (PMID 24738062, 2014). "Therefore, we hypothesized that the amplification and overexpression of BRF2 may contribute to lung SqCC tumorigenesis by contributing to increased cell growth and proliferation, representing a novel alternative mechanism of increasing Pol III transcription in cancer." (PMID 20668658, 2010).
tumor (14 papers, 2010 to 2025). "TUNEL staining confirmed tumor cell apoptosis in nude mice, and compared to the control group, BRF2 knockdown was associated with an increased level of tumor cell apoptosis." (PMID 40610422, 2025). "We also found that BRF2 expression was positively associated with tumor size, neoplasm recurrence, and poor prognosis in HCC." (PMID 37653482, 2023). "Further studies demonstrated that MALAT1 positively regulated the expression of transcription factor II B‐related factor 2 (BRF2), which was associated with tumor recurrence, large tumor size, and poor prognosis in HCC." (PMID 37653482, 2023). "It is possible that the loss of BRF2 functions in the primary tumor would result in the activation of alternative proliferation pathways in distant metastases during reversion of EMT." (PMID 27136531, 2016). "BRF2 promoted mitochondrial autophagy and reduced mitochondrial damage, which influences tumor apoptosis." (PMID 40610422, 2025). "The in vivo rescue experiments demonstrated that overexpression of SLC8A3 effectively restored the impaired tumor growth rate, volume, and weight in BRF2 knockout nude mice." (PMID 40610422, 2025). "To explore the molecular mechanism of MALAT1 in HCC, we screened target genes associated with MALAT1 (i.e., highly expressed in HCC tumor tissues and positively associated with poor prognosis in HCC patients) from TCGA database and identified the BRF2 gene." (PMID 37653482, 2023). "We next investigated a possible link between BRF2 expression and cellular signaling pathways, as well as immunoregulation and tumor infiltration." (PMID 34359683, 2021). "We detected the expression of BRF2 protein in the normal lung tissues, adjacent non-tumor tissues and tumor tissues by immunohistochemistry." (PMID 24523874, 2014). "Consistent with the microarray results, expression of BRF2 in primary tumors was significantly higher than that in the non-neoplasia tissues (p<0.001) with overexpression more common in SqCC than AC (p = 0.03), supporting our findings." (PMID 20668658, 2010). "Mirroring the findings from the clinical tumor specimens, BRF2 expression was strongly correlated with gene dosage with the two cell lines with amplification (HCC95 and H520) displaying the highest transcript levels." (PMID 20668658, 2010). "BRF2 knockdown significantly reduced the tumor growth rate, volume, and weight in nude mice." (PMID 40610422, 2025). "BRF2 in LUSC may promote tumor progression by inhibiting apoptosis, and animal experiments verified this result." (PMID 40610422, 2025). "Additionally, TUNEL staining revealed that SLC8A3 expression counteracted the effects of BRF2 knockout on tumor cell apoptosis in nude mice." (PMID 40610422, 2025). "For the BRF2-LIPIN1 pair, BRF2 is related to tumor angiogenesis." (PMID 27470995, 2016). "Our results highlight the potential role of BRF2 in tumor angiogenesis." (PMID 24523874, 2014). "In addition, univariate and multivariate analysis demonstrated that BRF2 protein over-expression and high MVD were significantly associated with tumor relapse." (PMID 24523874, 2014). "Through the integration of genetic and gene expression data for >330 clinical tumor specimens in conjunction with functional cell model studies, we identified BRF2 as the target of this amplification and a cell lineage-specific oncogene, the only such oncogene described for lung SqCC to date." (PMID 20668658, 2010). "Therefore, rescue experiments were performed by overexpressing SLC8A3 in BRF2 knockout cells to determine whether SLC8A3 is involved in the effect of BRF2 on tumor apoptosis." (PMID 40610422, 2025). "BRF2 was highly expressed in HCC tumor samples, and a positive relationship was identified between MALAT1 and BRF2 in HCC tumor samples." (PMID 37653482, 2023). "TFIIIB-related factor 2 (BRF2) is a subunit of TFIIIB complex, which plays critical rolesin promoting tumor progression and/or metastasis." (PMID 31964245, 2020).
tumor (continued). "Thesefindings were further confirmed by the result that miR-425-5p decreased BRF2 protein levelin A549 cells.Moreover, we found increased BRF2 expression in NSCLC tumor tissues compared with that inthe paired tumor-adjacent tissues." (PMID 31964245, 2020). "However, in multivariate analysis, only BRF2 expression could independently and significantly predict overall 5-year survival, despite the finding that high MVD was significantly associated with tumor recurrence." (PMID 24523874, 2014). "Taken together, our data support the assumption that BRF2 protein over-expression is common in early-stage NSCLC and significantly correlated with tumor angiogenesis and relapse." (PMID 24523874, 2014). "Importantly, BRF2 expression showed strong negative correlation withmiR-425-5p expression in NSCLC tumor tissues." (PMID 31964245, 2020).
adenocarcinoma (2 papers, 2014). A common cancer characterized by the presence of malignant glandular cells. "Univariate analysis demonstrated that the overall 5-year survival rate of patients with BRF2 protein high expression was significantly lower than that of the remaining patients among N1, T1-2, and adenocarcinoma (P = 0.008, P = 0.002, and P = 0.015, resp.)." (PMID 24738062, 2014).
BRF2 also shares sentences with these, for which no sentence is quoted: lymphoma (2 papers); adrenocortical carcinoma (1); bladder carcinoma (1); cervical cancer (1); COVID-19 (1); craniosynostosis (1); cutaneous melanoma (1); developmental delay (1); Immunodeficiency (1); Intellectual disability (1); intraductal cribriform breast adenocarcinoma (1); invasive ductal breast carcinoma (1); invasive lobular carcinoma (1); lobular carcinoma (1).